FTO (FTO alpha-ketoglutarate dependent dioxygenase)
Diseases named in the same sentence as FTO in open-access papers (continued):
Sharing a sentence is not in itself a finding about the gene and the disease.
type 2 diabetes (continued). "In the PREDIMED study, we focused on two SNPs strongly associated with obesity and type-2 diabetes: the FTO-rs9939609 and the MC4R-rs17782313 polymorphisms." (PMID 27598147, 2016). "We have previously confirmed the associations of genetic variants in HHEX, CDKAL1, VEGFA and FTO with type 2 diabetes in Han Chinese." (PMID 25587982, 2015). "The 16q12.2 locus in the first intron of FTO has been robustly associated with body mass index (BMI) and type 2 diabetes in genome-wide association studies (GWAS)." (PMID 24978468, 2014). "In this setting, many studies have investigated the relationship of the FTO rs9939609 polymorphism with insulin resistance and type 2 diabetes mellitus in the general population (HIV and HCV seronegative subjects)." (PMID 25367448, 2014). "For example, allele A of SNP rs9939609 in the FTO gene was reported to be associated with both increased BMI in various populations and elevated risk for type 2 diabetes." (PMID 25093408, 2014). "We first examined the LD relationship between FTO SNPs showing significant association with type 2 diabetes in Japanese GWAS and between those previously reported in European GWAS." (PMID 24978468, 2014). "FTO has well replicated associations with type 2 diabetes in numerous populations including those in India and Europe." (PMID 27099715, 2013). "Cardiovascular risk factors as type-2 diabetes mellitus, insulin resistance, and hypertension were associated with the risk allele A for FTO rs9939609 and the risk allele C for MC4R rs17782313, regardless body mass index." (PMID 23849767, 2013). "In an ethnically diverse sample of overweight and obese adults with type 2 diabetes, risk alleles at FTO rs1421085 predicted more eating episodes a day." (PMID 24040077, 2013). "After adjusting for BMI, the association with type 2 diabetes was completely abolished, suggesting that the FTO-type 2 diabetes association was mediated through BMI." (PMID 23134754, 2012). "Accordingly, the main finding and novelty of our results is that we have found that the association between the FTO rs9939609 polymorphism and type 2 diabetes depends on the diet consumed." (PMID 23130628, 2012). "Regarding the MC4R gene, there are fewer studies that have analyzed the association between the rs17782313 polymorphism (or a proxy) with type 2 diabetes than for the FTO gene, and the results are even less conclusive." (PMID 23130628, 2012). "When adherence to the MedDiet was low, carriers of the variant alleles had higher type 2 diabetes risk (OR=1.21, 95%CI: 1.03-1.40; P=0.019 for FTO-rs9939609 and OR=1.17, 95%CI:1.01-1.36; P=0.035 for MC4R-rs17782313) than wild-type subjects." (PMID 23130628, 2012). "These variants represent those with the strongest reported effects on type 2 diabetes risk and, for the FTO variant, BMI." (PMID 20929593, 2010). "FTO has attracted a huge interest, as it was identified by genome-wide studies as a susceptibility gene for type 2 diabetes." (PMID 21286314, 2010). "And we also found the WFS1 rs10010131 and FTO rs8050136 showed trends towards association to type 2 diabetes in our samples (0.05<P<0.1)." (PMID 19862325, 2009). "Finally, decreased levels of m6A methylation in blood sample of patients with type 2 diabetic are associated with increased expression levels of the demethylase FTO that correlates positively with blood glucose concentration." (PMID 35053407, 2022). "FTO was initially recognized as a susceptible gene for type 2 diabetes." (PMID 33461172, 2021). "The FTO gene was discovered in 2007 in a genome-wide association study of type 2 diabetes." (PMID 34368154, 2021). "FTO Haplotypes involving index SNPs and their association with BMI and type 2 diabetes." (PMID 24978468, 2014). "Over the past few years, the association of the FTO locus has been repeatedly replicated, not only for BMI, but also for obesity risk, body fat percentage, waist circumference, and other obesity-related traits, in particular type II diabetes." (PMID 24348519, 2013).
type 2 diabetes (continued). "Besides its close association with adiposity, FTO has been shown to be associated with susceptibility to type II diabetes." (PMID 23835106, 2013). "However, when adherence to the MedDiet was high, the higher risk of type 2 diabetes in subjects carrying variant alleles at both the FTO and the MC4R loci, were completely blunted (OR: 0.86; P=0.266)." (PMID 23130628, 2012). "We found a relevant interaction between adherence to the MedDiet and these polymorphisms in determining type 2 diabetes, which was significant both for the FTO (P-interaction=0.039) and for the MC4R (P-interaction=0.009) as well as for their aggregate score (P-interaction=0.006) (Model 1)." (PMID 23130628, 2012). "However, in other reports the association of the FTO minor allele with type 2 diabetes risk persisted even after adjustment for BMI increasing the evidence that the FTO can also be considered a diabetes-prone gene." (PMID 23130628, 2012). "Thus, when the dietary pattern departed from the traditional MedDiet (low-adherence to the MedDiet), the FTO rs9939609 was significantly associated with higher type 2 diabetes risk, while a good adherence to the MedDiet blunted this association." (PMID 23130628, 2012). "Likewise, in a Scandinavian population, the FTO rs9939609 was associated with both prevalent type 2 diabetes (OR 1.13; P<0.001) and the risk of developing incident type 2 diabetes (OR 1.16; P<0.001) having comparable results." (PMID 23130628, 2012). "Human FTO gene variants are associated with body mass index and type 2 diabetes." (PMID 19680540, 2009). "Moreover, FTO encodes an m6A RNA demethylase and is involved in several biological processes and metabolic pathways, and overexpression of the FTO gene was observed in type 2 diabetes." (PMID 39057082, 2024). "The aim of this study was to investigate the association between PA and incidence of LADA compared with the associations regarding type 2 diabetes, as well as whether these associations are modified by HLA, FTO, or TCF7L2 genotypes and potential underlying mechanisms." (PMID 32835373, 2020). "It is known that single nucleotide polymorphisms (SNPs) in the first intron of FTO are associated with increased body weight, adiposity and type 2 diabetes mellitus (T2DM)." (PMID 28933365, 2017). "Finally, variation in other genetic or environmental factors that contribute to the development of type 2 diabetes may underlie the apparently disparate effects of the FTO gene in African-Americans and whites in the ARIC cohort." (PMID 20502638, 2010). "For instance, by using variants in the FTO locus as instruments and plasma CRP level as the proxy exposure, the authors inferred a putative causal link between altered FTO function (proxied by variant effect on CRP) and type 2 diabetes risk." (PMID 41004399, 2025). "Elevated FTO mRNA expression is detected in peripheral blood samples from type 2 diabetic patients, resulting in decreased m6A content and disturbed glucose metabolism." (PMID 38297099, 2024). "This study investigated the association of SNPs ADRB3(rs4994), ABCC8 (rs1799854),FTO (rs8050136) and TCF7L2(rs7901695 and rs12255372) with type 2diabetes in a sample of the Amazonian population." (PMID 39133695, 2024). "Numerous studies have indicated that a variant (rs8050136) of the fat mass-associated gene, FTO, is associated with both GDM and Type 2 diabetes mellitus(T2DM)." (PMID 38033012, 2023). "The aim of this study was to investigate the correlation between polymorphisms in the FTO gene and TSH level in Uyghur patients with type 2 diabetes in the Xinjiang region." (PMID 34258276, 2021). "This study examined the association of the polymorphic markers of the genes KCNJ11, SLC30A8, CDKAL1, CDKN2B and FTO with type 2 diabetes mellitus in Russia." (PMID 28717589, 2017).
type 2 diabetes (continued). "We found statistically significant gene-diet interactions between the FTO-rs9939609 SNP and the MC4R-rs17782313 SNP, separately, with the MedDiet score in determining type 2 diabetes risk at baseline." (PMID 27598147, 2016). "We genotyped FTO rs9939609 SNP in 296 patients with type 2 diabetes from the Out Patient Department (OPD) of Baqai Institute of Diabetology and Endocrinology (BIDE)." (PMID 25878631, 2015). "In agreement, we recently found an increased FTO expression in both human skeletal muscle and subcutaneous adipose tissue during type 2 diabetes." (PMID 24410832, 2014). "For example, FTO variation was initially identified in relation to type 2 diabetes, with subsequent recognition that this was because the genetic variant related to BMI, which in turn increased the risk of type 2 diabetes." (PMID 25064373, 2014). "The association of the FTO-rs9939609 and MC4R-rs17782313 polymorphisms with type 2 diabetes depends on diet, and a high adherence to the MedDiet is able to counteract a genetic predisposition to cardiovascular disease." (PMID 25407792, 2014). "The aim of this study was to investigate the association between FTO rs9939609, MC4R rs17782313 with anthropometric indicators, blood pressure, and type-2 diabetes in patients with hypertension." (PMID 23849767, 2013). "This study aimed to investigate the association of FTO rs9939609 and MC4R rs17782313 with anthropometric indexes, BP, and type 2 diabetes mellitus among hypertensive patients." (PMID 23849767, 2013). "A study reported that the CpG site in the first intron of the FTO gene was hypomethylated in type 2 diabetes cases relative to controls." (PMID 23130628, 2012). "These novel results suggest that the association of the FTO-rs9939609 and the MC4R-rs17782313 polymorphisms with type 2 diabetes depends on diet and that a high adherence to the MedDiet counteracts the genetic predisposition." (PMID 23130628, 2012). "As far as we know this is the first time that a significant interaction between the FTO rs9939609 and diet in determining type 2 diabetes has been reported in humans." (PMID 23130628, 2012). "Adherence to a Mediterranean dietary pattern attenuates the association between FTO and MC4R polymorphisms and type 2 diabetes risk; conversely, among individuals with low Mediterranean-diet adherence, carriers of the FTO and MC4R risk alleles exhibit a significantly higher risk of type 2 diabetes." (PMID 41190158, 2025). "An increasing number of studies have reported that FTO-mediated epigenetic modifications play an important role in the regulation of immune responses and metabolic diseases, such as acute myeloid leukemia, heart failure, and type 2 diabetes." (PMID 41367876, 2025). "The results of liquid chromatography/electrospray ionization/tandem mass spectrometry revealed that high FTO expression in type 2 diabetes mellitus (T2DM) patients accompanied by increased mRNA expression levels of key genes of glucose metabolism (FOXO1, G6PC, and DGAT2)." (PMID 36830642, 2023). "The strongest shared locus between type 2 diabetes and sleep straits was FTO (lead SNP rs8047587)." (PMID 35203577, 2022). "In 2007, the FTO gene was identified in a type II diabetes genome-wide relationship research." (PMID 36120562, 2022). "The traditional Mediterranean diet pattern, which may protect against type 2 diabetes, is low in saturated fat and includes foods rich in fiber, including vegetables, fruits, legumes, and nuts, which showed interactions with FTO rs9939609." (PMID 34829664, 2021). "The FTO gene affects adiposity, insulin resistance and the development of type 2 diabetes mellitus." (PMID 32050935, 2020). "By in silico replication using SUMMIT consortium data for type 2 diabetes, the association of FTO variants with diabetic nephropathy was not replicated in European patients with type 2 diabetes." (PMID 30566433, 2018).
type 2 diabetes (continued). "The initial study reported that the significant association of FTO variants and type 2 diabetes risk no longer exists after adjusting adiposity." (PMID 30388740, 2018). "The genome wide association studies have identified various susceptibility genes, including several type 2 diabetes mellitus (T2DM) such as PPARG, TCF7L2, FTO, CDKN2A/2B, and IRS1 etc. to be associated with the risk of T2DM, though their definite relation with GDM remains to be explored further." (PMID 28083030, 2016). "There were exceptions for the FTO–BMI association and the CDKAL1–type 2 diabetes association." (PMID 26961502, 2016). "A recent study in north Indian Sikhs demonstrated a strong association of FTO variants with type 2 diabetes, which did not seem to be mediated through BMI." (PMID 24156506, 2013). "Studies in the Han Chinese population failed to establish consistency of association between FTO variants and type 2 diabetes." (PMID 23990951, 2013). "There is increasing evidence that the MedDiet protects against type 2 diabetes, so it is not surprising that high adherence to this dietary pattern cancels the effects of greater genetic susceptibility to diabetes in FTO risk allele carriers." (PMID 23130628, 2012). "Thus, although it is necessary to investigate the effect of the interaction between the level of adherence to the MedDiet and the FTO rs9939609 on incident type 2 diabetes cases in future studies, it is foreseeable that the results would be similar." (PMID 23130628, 2012). "Then, outstanding among the dietary factors that could modulate the effect of the FTO rs9939609 and the MC4R rs17782313 polymorphisms on type 2 diabetes, is the Mediterranean diet (MedDiet)." (PMID 23130628, 2012). "We did not observe statistically significant differences in genotype frequencies of the FTO rs9939609 or the MC4R rs17782313 polymorphisms between subjects with type 2 diabetes and non-diabetic subjects." (PMID 23130628, 2012). "We have previously examined common genetic variation in several candidate gene loci (i.e., KCNQ1, KCNJ11, CDKAL1, and FTO genes) and confirmed some but not all of their associations with type 2 diabetes in the SDS." (PMID 21062480, 2010). "Our finding also supported that WFS1 and FTO might participate in the pathogenesis of type 2 diabetes, although the effects we detected on rs10010131 and rs8050136 were not statistically significant." (PMID 19862325, 2009). "Similarly, FTO-rs9939609 polymorphism (A allele carriers) has been linked to greater improvements in BMI and diastolic blood pressure after EGCG supplementation in patients with type 2 diabetes, highlighting the role of host genetics in therapeutic response." (PMID 41106481, 2025). "Indeed, several recent studies indicate an important role for cis-regulatory mutations in disease, not only in cancer (e.g., TERT, TAL1), but also in complex diseases (e.g., type II diabetes FTO locus, Parkinson’s disease) and in familial disorders (e.g., preaxial polydactyly)." (PMID 28854983, 2017). "In patients with type 2 diabetes mellitus (T2DM), a CpG dinucleotide in the first intron of the FTO gene was hypomethylated (−3.35%) and the odds of belonging to the T2DM group increased by 6.1% for every 1% decrease in DNA methylation." (PMID 28289476, 2017). "In Europeans, FTO increased the risk of patients with type 2 diabetes through its impact on BMI while the reports from South Asian population showed that the risk of patients with type 2 diabetese associated with SNP of FTO gene was not dependent on BMI." (PMID 25878631, 2015). "A majority of genes associated with type 2 diabetes from this meta-analysis (ADCY5, CDKAL1, CDKN2A/B, HHEX, IGF2BP2, SLC30A8, TCF7L2 and KCNQ1) are involved in pancreatic beta cell function, while two are implicated in insulin sensitivity (PPARG) and adiposity (FTO)." (PMID 25145545, 2014). "Therefore, FTO is well established as a susceptibility gene of type 2 diabetes in Caucasians, but not in Chinese." (PMID 23990951, 2013).
type 2 diabetes (continued). "The fact that the genome-wide score with the known regions removed also showed strong association with type 2 diabetes shows that these associations do not solely reflect the effect of variants within FTO and other BMI genes known to be reliably associated with type 2 diabetes." (PMID 24204319, 2013). "Considering that dysregulation in DNA, methylation has been suggested as one relevant epigenetic mechanism in type 2 diabetes and that both the FTO and the MC4R genes are regulated by methylation, the MedDiet might modulate the effect of these genes through epigenetic mechanisms." (PMID 23130628, 2012). "However, in 2007, several reproducible genome-wide association studies (GWASs) confirmed these well-established susceptibility genes and identified a number of new loci (SLC30A8, HHEX, CDKN2A/B, IGF2BP2, GCKR, FTO, and CDKAL1) at which common variants influence risk of type 2 diabetes in Europeans." (PMID 20161779, 2010). "It should also be noted that the non-significance of FTO SNP may be partly explained by the similar BMI between the cases and controls in our samples, as FTO variant increases type 2 diabetes risk mainly through increasing BMI." (PMID 19862325, 2009). "The Diabetes Genetics Initiative used a tightly matched case-control sample in the discovery phase, where cases and controls had been matched for body mass index and thus it is not surprising that there was no residual effect of this FTO variant on the risk of type 2 diabetes." (PMID 17786212, 2007). "Therefore, if FTO can regulate LEP and LEPR expression, this could also lead to an altered expression of IL-6 and TNF-α and a significant susceptibility to the development of chronic diseases such as type 2 diabetes mellitus." (PMID 38474283, 2024). "In contrast, m6A levels in the peripheral blood of individuals with Type 2 diabetes mellitus (T2DM) are lower than in controls, with concomitantly high m6A ‘eraser’ FTO gene expression." (PMID 36831575, 2023). "In a recent study, demethylases FTO have been demonstrated to positively correlate with methyltransferases methyltransferase complex (METTL3, METTL14, and WTAP) in patients with type 2 diabetes." (PMID 32583611, 2020). "We further evaluated the cumulative effect on type 2 diabetes of these 4 SNPs, in combination with 5 SNPs at HHEX, CDKAL1, VEGFA and FTO reported previously." (PMID 25587982, 2015). "In conclusion, we described for the first time a statistically significant gene-diet interaction of the FTO rs9939609 and MC4R rs17782313 with adherence to the MedDiet on type 2 diabetes." (PMID 23130628, 2012). "Recently, several genome-wide and candidate gene association studies have identified many novel genetic loci for type 2 diabetes (T2D); among these genes, CDKAL1, IGF2BP2, SLC30A8, CDKN2A/B, HHEX, FTO, TCF2, KCNQ1, and WFS1 are the most important." (PMID 20509872, 2010). "Type 2 diabetes was associated with TCF7L2 (RRpooled 1.46, 95% CI, 1.35-1.59) and FTO (RRpooled 1.15, 95% CI 1.06-1.26) but not with HLA (RRpooled 0.94, 95% CI, 0.86-1.02)." (PMID 32835373, 2020). "For type 2 diabetes, the association with PA did not appear to be modified by either TCF7L2, FTO, or HLA." (PMID 32835373, 2020). "Furthermore, association of FTO variants with type 2 diabetes mellitus (T2DM), independent of body mass index (BMI), has been demonstrated in East and South Asians and Scandinavians." (PMID 32076432, 2019). "Results were independent of sex, age or suffering from hypertension, diabetes mellitus type 2 or dyslipidemia and were attenuated in carriers of PLIN4, FTO, Trp64Arg polymorphisms." (PMID 29361938, 2018). "Consistent with previous studies, we find a 50% lower incidence of type 2 diabetes in individuals engaging in high PA vs those who are sedentary, and the risk reduction seemed equally strong in carriers and noncarriers of the TCF7L2 and FTO risk variants." (PMID 32835373, 2020).
type 2 diabetes (continued). "The association of type 2 diabetes mellitus (T2DM) with the KCNJ11, CDKAL1, SLC30A8, CDKN2B, and FTO genes in the Russian population has not been well studied." (PMID 28717589, 2017).